TGFB2 (transforming growth factor beta 2)
Diseases named in the same sentence as TGFB2 in open-access papers (continued):
Sharing a sentence is not in itself a finding about the gene and the disease.
tumor (continued). "miR-148a downregulated the expression of TGFB2 in gastric cancer cells, which contributed to the inhibition of tumour cell proliferation and metastasis." (PMID 38067167, 2023). "We next sought to identify the molecular mechanism for the upregulation of TGFB2 mRNA expression levels in 41 DIPG tumor samples with a focus on transcription factors/DNA binding proteins that are known to augment TGFB2 gene expression." (PMID 36980562, 2023). "In an acidic tumour microenvironment, the expression of miR-7-5p was reduced, alleviating its suppressive effect on the TGFB2 mRNA 3′ untranslated region (3′UTR)." (PMID 38067167, 2023). "The purpose of the present study was to evaluate the clinical significance of amplified expression levels of transforming growth factor beta 2 (TGFB2) in the tumor tissue specimens from DIPG patients." (PMID 36980562, 2023). "Even in this case, we identified CNAs in genes potentially related to tumor recurrence, such as TGFB2 and TMPRSS2." (PMID 35841413, 2022). "The results showed high expression of HIF1A family and pro-angiogenesis related genes in the microenvironment of patients in the high TGFβ2 group, which can be inferred to be a hypoxic environment within the high TGFβ2 expressing tumor tissues." (PMID 35620459, 2022). "TGFβ1, TGFβ2, and TGFβ3 protein expressions were distributed in similar regions, with higher levels in the cell cytoplasm, and a small amount in the tumor stroma." (PMID 36119489, 2022). "We found that FOXP3 is a good prognostic factor for patients with high IL-33 and TGFb2 in the tumor." (PMID 35565267, 2022). "The analyses performed in this study concluded that the expression of TGFβ1 and TGFβ2 increased with increasing tumor grade and, thus, malignancy." (PMID 35454784, 2022). "Given the important role of TGFβ2 in the tumor microenvironment, we further analyzed the relationship between TGFβ2 and immune cell infiltration and cytokines (receptor, chemokine, immunoinhibitor, immunostimulator and MHC)." (PMID 35620459, 2022). "It is possible that rapid tumor growth noted in our study was attributable to the use of anti-PD-L1 therapy and by removal of circulating TGFβ1 and TGFβ2 with the TGFβ trap of BA." (PMID 36382087, 2022). "The results showed that TGFβ2 was positively correlated with stromalscore and CAFs and negatively correlated with tumor purity in several datasets, which was consistent with the results of the analysis in STAD." (PMID 35620459, 2022). "The fact that we observed JUNB-dependent repression of TGFB2 in the experiments presented above led us to wonder about the possible disturbance of TGFB2 downstream signaling in JUNB-overexpressing tumor cells growing in a TGFB2-rich environment." (PMID 36494864, 2022). "In the tumor microenvironment we analyzed the relationship between TGFβ2 and tumor stemness, EMT and ESTIMATE scores, respectively, with similar results between different pan-cancers." (PMID 35620459, 2022). "Other approaches include whole cell vaccine based methods that use autologous tumor cells expressing an anti-sense to TGFβ2 or tumor-specific CD8 + T cells modified to express a dominant-negative TGFβRII (non- ovarian cancers)." (PMID 33590419, 2021). "RNA-seq data also demonstrated that several genes related to adoptive immune systems which have pro-tumor action, such as TGFβ2, TGFBI, TGFBR1, TGFBR3, PLAU, IL-1β, and IL-33 are higher in Pn-positive cells than Pn-negative cells." (PMID 34680221, 2021). "Transforming growth factor β2 (TGFB2), one of the isoforms of TGF-β, has been reported to be associated with various neoplasms." (PMID 34136553, 2021). "The role of TGFB2 in BC progression is ambiguous, as it was shown to display tumor-suppressing and -enhancing effects." (PMID 34063128, 2021). "We examined the differences between the copy number of TGFB2 and ploidy level and in the relative copy number of TGFB2 for each donor of multiple tumor types." (PMID 34344966, 2021).
tumor (continued). "We propose a new mechanism through which tumor cells utilise TGFβ2 to promote production of sCTLA-4 as a novel mechanism of immune evasion and further, highlight the urgent need to examine the relevance of sCTLA-4 to immune checkpoint inhibitor therapy." (PMID 35069536, 2021). "Firstly, we determined TGFβ2 expression in 186 cases of primary ESCC tumor tissues and 160 cases of matched adjacent normal tissues by immunohistochemistry." (PMID 32832354, 2020). "Tumor cell dormancy can be fueled through distinct cues, such as the protein‐coding genes, TGFβ2 and NF2F1." (PMID 32392629, 2020). "We further used the TCGA and TIMER databases to assess how TGFβ2 expression differs in particular tumour types." (PMID 32530106, 2020). "We found that there was a significant correlation between TGFβ2 expression and the tumour purity in 24 cancer types, and between TGFβ2 expression and B cell infiltration in 14 cancer types." (PMID 32530106, 2020). "By screening of a library consisting of 429 bioactive compounds, imperatorin is verified as a novel TGFβ2 inhibitor, with robustly suppressive effect on tumor metastasis in multiple mice models." (PMID 32832354, 2020). "A small molecule library consisting of 429 bioactive compounds was taken to screen the drug candidates capable of blocking TGFβ2 pathway and suppressing tumor invasion, simultaneously, in ESCC." (PMID 32832354, 2020). "The in vivo rescue experiment was established and the data showed that treatment with imperatorin resulted in the delay of tumor metastasis, whereas intravenous injection of TGFβ2 significantly abolished this effect." (PMID 32832354, 2020). "The functional role of TGFβ2 and therapeutic implication of imperatorin in tumor metastasis and microenvironment were investigated in vitro and in vivo." (PMID 32832354, 2020). "These exosomes significantly increased M2 macrophage-related cytokines such as IL10 and transforming growth factor-beta 2 (TGFB2), and modulate macrophages to a tumor-promoting M2 phenotype." (PMID 33363016, 2020). "Among all of the genes, the transcript level of transforming growth factor β2 (TGFβ2) was changed in different tumor stages, T categories, grades, and patients’ survival states, and up-regulated in patients with GC compared with the normal." (PMID 33115518, 2020). "In this study, we found the level of TGFβ2 was not only significantly changed among different patients’ tumor stages, states, T categories, and grades but also up-regulated in patients with GC vs the normal." (PMID 33115518, 2020). "The majority of the tumor tissues had stronger TGFβ2 immunostaining than corresponding normal tissues." (PMID 32832354, 2020). "In contrast, 92.50% (148/160) of normal tissues, whereas only 61.83% (115/186) of tumor tissues, showed low TGFβ2 expression." (PMID 32832354, 2020). "Among these, TGFβ2 was identified as crucial for the induction of dormancy in disseminated tumor cells and emerged as highly upregulated in ZEB2-overexpressing tumors." (PMID 31910865, 2020). "In metastatic breast cancer models, TGFβ2 and TGFβ3 expressed by disseminated tumor cells induce periostin expression in lung fibroblasts and endothelial tip cells." (PMID 33014869, 2020). "38.17% (71/186) of tumor tissues displayed high TGFβ2 expression, but only 7.50% (12/160) of normal tissues had high TGFβ2 expression." (PMID 32832354, 2020). "Measurements of 36 different chemokines in the culture medium revealed a significant decrease in the secretion of CCL5, CCL8, CXCL1, CXCL2, CXCL5, and TGFβ1 and a significant increase in TGFβ2 secretion by TB9-Fhit transfected tumor cells." (PMID 32545680, 2020). "ASK1 has been identified as the key mediator in TGFβ2 downregulation-induced death that induces cytotoxic tumor cell death via p38/JNK activation and (or) induction of ER stress." (PMID 31795071, 2019).
tumor (continued). "Other than EMT-regulation, TGFβs have profound effects on tumor micro-environment, the role of TGFβ2 in DDB2-mediated EMT-regulation in HNSCC tumors needs further investigation." (PMID 30410671, 2018). "This is in contrast to other studies showing that blocking TGFβ1 and TGFβ2 alone was sufficient to improve anti-tumor efficacy in murine tumor models." (PMID 29721396, 2018). "The tumor was capable of modifying the SN environment to be tolerogenic by forming chronic inflammation, causing the synergistic effects of ICAM-1 and TGFβ2 signal, together with exhaustion and Tc2 skewed environment, to suppress CD8+ T cells cytotoxicity." (PMID 29966014, 2018). "TGFβ1 and TGFβ2 can either act as a tumor promoter in diverse cancer models or as a tumor suppressor by inhibiting cell proliferation." (PMID 29221185, 2017). "Here, we show that through shRNA knockdown studies, TGFβ2 directly mediates the survival of the adaptive EGFR-TKI drug-escaping tumor cells, and that it also directly regulates the mitochondrial BCL-2/BCL-xL expression downstream, but not BIM." (PMID 27852038, 2016). "In contrast, the levels of TGFβ2 mRNA in both borderline and invasive tumor cells were significantly lower than the levels in normal ovarian surface epithelial cells and benign tumors (P < 0.001)." (PMID 26684027, 2016). "High TGFB2, TGFB3 and TGFBR2 mRNA levels in tumours were generally associated with better prognosis for patients, especially those diagnosed with lymph node-negative diseases." (PMID 26703884, 2015). "Expanding on these findings, shRNA-mediated knockdown of Tgfb2 expression in SCC FAK-WT cells also influenced tumor growth." (PMID 26406376, 2015). "The beneficial effect of having higher expression of TGFB2 mRNA in the tumours seemed to be in the later years after diagnosis." (PMID 26703884, 2015). "In the patients, the hazard ratio of death for having tumours expressing the highest 60 % of TGFB2 mRNA levels versus having tumours expressing the lowest 40 % of TGFB2 mRNA levels for the first 9 years after diagnosis was 0.5 (95 % CI: 0.31 – 0.81)." (PMID 26703884, 2015). "The p38 stress response pathway activated by TGFβ2 and other cues has been proposed as a regulator of tumor cell dormancy." (PMID 25301725, 2014). "TGFB2 (transforming growth factor beta-2) is a secreted protein that can act as a tumor suppressor in early stages of tumorigenesis or as a metastasis promoting factor in advanced cancers." (PMID 23213280, 2012). "Addition of TGFβ2 to hGBM tumor cell cultures resulted in an increase in the number of sphere-initiating cells." (PMID 21246056, 2011). "This was in contrast to TGFβ1 that remained high throughout and TGFβ2 that was highest in the primary tumour." (PMID 17565341, 2007). "Our results also indicated a direct correlation between the MUC4 expression and the levels of TGFβ2 transcripts in the CD18/HPAF tumours, as well as in CD18/HPAF cells in vitro." (PMID 14760381, 2004). "We found that OT tumours showed TGFβ2 expression with a range two-fold higher than the parental cell lines CD18/HPAF." (PMID 14760381, 2004). "Specifically, in the early stages of tumorigenesis, TGFβ2 may inhibit tumor growth by suppressing cell proliferation, inducing apoptosis, and inhibiting angiogenesis." (PMID 40151835, 2025). "To determine whether RT induces the expression of TGF‐β and VEGF, we analyzed the transcription level of Tgfb1, Tgfb2, Tgfb3, and Vegfa using RNA‐seq data of irradiated versus non‐irradiated 4T1 tumor tissues." (PMID 40470716, 2025). "Furthermore, distinct responses to TGFβ2 exist between healthy endothelial cells and TECs from various tissues, tumour types, and even subclones within the same culture 114,115." (PMID 40083695, 2025). "Age-related epigenomic alterations might influence this process by adding methyl groups to TGFB2, thereby dampening its expression and shifting the tumor toward a more “epithelial-like” and less immunosuppressive state." (PMID 40650134, 2025).
tumor (continued). "The age-related differences in TGFB2 expression and methylation may reflect a shift in the tumor microenvironment and immune response, particularly in the context of T cell engagement and mesenchymal–epithelial transition." (PMID 40650134, 2025). "This suggests that acidic tumor microenvironment-induced changes in miRNAs and TGFβ2 may contribute to tumor progression and metastasis." (PMID 39992949, 2025). "Our analysis suggests that when considering both TGFB2 and IFI27 gene methylation as prognostic markers, the mRNA correlation with gene methylation yielded potential diagnostic markers markedly upregulated in tumor tissues." (PMID 40565031, 2025). "Genes were filtered based on the tumor-specific expression patterns and Cox models with highly significant interaction terms to identify mRNA expression of genes that amplified the impact of TGFB2 methylation." (PMID 40565031, 2025). "We shed light on the role of miR-193b-3p and TGFβ2 in the acidic tumor microenvironment." (PMID 39992949, 2025). "Similarly, we found that the combination of TGFB2 inhibitor imperatorin with gemcitabine significantly improved tumor response in gemcitabine-resistant PDAC PDX." (PMID 38914663, 2024). "Furthermore, along with the low expression of neutrophil markers, Tgfb2 expression was lowered in KPN KF tumours." (PMID 38168062, 2024). "TGFβ2‐ or Snail1‐knockdown greatly delayed xenograft tumour growth." (PMID 38299307, 2024). "MARCO was found to be co-regulated with IFI27 expression and exhibited a similar parameter profile for the multivariate Cox proportional hazards model, suggesting that the detection of MARCO in tumor tissue would limit the impact of TGFB2 knockdown for OS improvements in PDAC patients." (PMID 39457004, 2024). "Importantly, tumor cells at the invasive margin, communicated with Detox-iCAF through the TGFβ2/TGFBR2 ligand-receptor pair." (PMID 38561380, 2024). "Similarly, IHC staining revealed that TGFB2 expression was elevated in PDX_GEM compared to PDX_PBS tumor tissue." (PMID 38914663, 2024). "Furthermore, it has been verified that NOX4 and TGFB2 exhibit elevated expression levels in tumor tissues relative to normal tissues." (PMID 39314752, 2024). "Oil red O staining of PDX tumor tissue indicated that inhibition of TGFB2 could decrease lipid accumulation." (PMID 38914663, 2024). "We selected two additional tumor models, T11‐UV and T11‐Apobec, that displayed a high expression of Tgfb1 (both tumor models) and Tgfb2 (T11‐UV), high expression of Vimentin (Vim) and fibrotic marker (Pik3ca), and low expression of Cd36 and apoptosis regulator Bcl2." (PMID 39553439, 2024). "As abnormal lipid metabolism has been suggested to be involved in tumor progression, we wondered whether TGFB2 could affect lipid metabolism in PDAC gemcitabine-resistant cells." (PMID 38914663, 2024). "Worse survival outcomes in pbDMG patients when comparing high versus low TGFB2 levels in the context of low IFNGR2 levels suggest that the abrogation of the TGFB2 mRNA expression in the immunologically cold tumor microenvironment can be used to treat pbDMG patients." (PMID 38255296, 2024). "Another mechanism by which TGFβ2 triggers tumor metastasis is by promoting angiogenesis." (PMID 38531630, 2024). "We have now extended that study with an updated cohort of pbDMG patients who exhibited high levels of tumor TGFB2 mRNA in combination with low levels of mRNA coding for IFN-γ-targetable receptors, and signaling molecules showed worse survival outcomes in pbDMG patients." (PMID 38255296, 2024). "Other BBB-disrupting or BBB-bypassing strategies might also be potentially helpful in effective tumor delivery of TGFB2-directed RNAi therapeutics in DIPG patients." (PMID 36980562, 2023). "Notably, DIPG patients with high levels of TGFB2 mRNA expression in their tumor samples had significantly worse overall survival (OS) and progression-free survival (PFS)." (PMID 36980562, 2023).
tumor (continued). "Notably, tumor samples from DIPG patients expressed significantly higher levels of TGFB2 mRNA than control pons samples, but the TGFB1, as well as TGFB3 mRNA levels in DIPG samples were significantly lower than in the control pons samples." (PMID 36980562, 2023). "In addition, we observed that permethrin represses the expression of the TGFB2 gene in BMMCs, which has a tumor suppressor function." (PMID 37047231, 2023). "By contrast, CXCL1, CXCL2, CCL2 and TGFB2 with defined pro-tumorigenic roles are more highly expressed by EA1 tumor cells at baseline and may antagonize anti-tumorigenic effects of CD8+ T cells that do infiltrate this model." (PMID 36739466, 2023). "Vigil (gemogenovatucel-T) is a novel plasmid engineered autologous tumor cell immunotherapy designed to knock down the tumor suppressor cytokines, TGFβ1 and TGFβ2, augment local immune function via increased GMCSF expression and enhance presentation of clonal neoantigen epitopes." (PMID 36051466, 2022). "In addition, TGFβ2 was positively correlated with stromalscore, immunescore and ESTIMATEScore and negatively correlated with tumor purity in a variety of tumors including STAD." (PMID 35620459, 2022). "Cytokines present in the tumor microenvironment, including TGFβ2, may influence tumor cell invasion." (PMID 35454784, 2022). "Hypoxia, as one of the important features of tumors, plays an important role in cancer progression; therefore, high expression of TGFβ2 may also be indirectly involved in tumor progression by regulating hypoxia-related genes." (PMID 35620459, 2022). "Interestingly, the bone-derived transforming growth factor (TGF) β1 and TGFβ2 have been demonstrated to exert opposite functions on the behaviour of tumour cell dormancy in the bone marrow." (PMID 36307871, 2022). "TGFβ2 also affects the negative regulation of macrophage cytokine production, which may be related to a reduced immune response within the tumor." (PMID 35454784, 2022). "The results of this study showed that TGFβ2 was negatively correlated with M1 macrophage markers and positively correlated with M2 macrophage markers, showing an overall M2 macrophage phenotype that promotes immune escape of tumor cells." (PMID 35620459, 2022). "TGFβ1 facilitates rapid tumour proliferation, while TGFβ2 promotes tumour cell dormancy." (PMID 36307871, 2022). "In TNBC, high TGFB2 expression is associated with poor prognosis and TGFB inhibition in BC cell lines may decrease tumor invasion." (PMID 35122700, 2022). "Interactions between the Growth Arrest Specific 6 (GAS6) factor produced by osteoblasts and the Axl tyrosine kinase receptor expressed by disseminating prostate cancer cells, mediated the TGFβ2 signaling pathway and promoted dormancy of the tumor cells in the bone marrow niche." (PMID 35418981, 2022). "In view of this, the key role of TGFβ2 in tumor progression and development seems to be undeniable." (PMID 35454784, 2022). "At the invasive tumor front, TGFB2 was the only gene with inverse expression to the miR-200 family." (PMID 34046357, 2021). "Furthermore, we found that dormant residual tumor cells in vivo exhibit increased expression of Tgfbr3 (TGFβR-III), as well as its ligand Tgfb2 (TGFβ-II), and markedly decreased expression of Plaur (uPar) compared to both primary and recurrent tumor cells." (PMID 34088357, 2021). "However, high expression of oncogenic factors including IGFBP2, PGF, and TGFB2 was found specifically in subset 4, suggesting a different functional role of fibroblasts in liver metastasis compared to the primary tumor." (PMID 34671197, 2021). "Thus, a number of questions still remain in order to completely understand the regulation of TGFB2 and its interaction with pathways activated in the course of tumor progression." (PMID 34063128, 2021). "The novel tumor escape mechanism inhibits perforin expression in CD8+T cells mediated by TGFB2." (PMID 33195410, 2020).